HIF1A (hypoxia inducible factor 1 subunit alpha)
Diseases named in the same sentence as HIF1A in open-access papers (continued):
Sharing a sentence is not in itself a finding about the gene and the disease.
tumor (continued). "HIF-1α inactivation increased TRAIL sensitivity in hypoxia-induced TRAIL-resistant tumor cells." (PMID 32848609, 2020). "HIF-1α accumulation is translocating into the nucleus to increase transcription of downstream signaling, leading to neoangiogenesis, metabolic switch, cell propensity to migrate, and tumor cell stemness features." (PMID 33092063, 2020). "The results showed that the positive stain of CHCHD2 and HIF-1a were 94.7% (198/209) and 95.7% (200/209) in tumor tissues, there were significantly higher than that in adjacent non-cancerous tissues 11.0% (23/209) and 68.9% (144/209), (P = 0.000, P = 0.000) respectively." (PMID 32054470, 2020). "Importantly, HIF-1α also controls the expression of alarmin receptors in tumor cells that can bind to and be activated by alarmins." (PMID 32290386, 2020). "Importantly, expression of the invasion and angiogenesis genes, S100A10, SERPINE1, and VEGFA, increased with tumor grade, and this was also observed for HIF-1α." (PMID 32867190, 2020). "The studies presented that HDAC4 played an important role in hypoxic induced angiogenesis, and that pharmalogical inhibition and shRNA against HDAC4 offered a new strategy in anti-cancer therapy through decreasing HIF-1α expression and inhibiting angiogenesis in tumor." (PMID 32354322, 2020). "The rapid proliferation of cancer cells within tumor tissue creates a hypoxic condition that triggers the angiogenic program to upregulate hypoxia-inducible factor (HIF)-1α and downstream vascular endothelial growth factor (VEGF), leading to tumor angiogenesis and tumor progression." (PMID 32486019, 2020). "These tumor cells experienced hypoxic conditions as indicated by the high levels of HIF-1α." (PMID 30367150, 2019). "It is noteworthy that ablation of HIF1a in the pancreatic tissue dramatically boosts malignant progress of KrasG12D-driven PanIN by recruiting a specific subgroup of B cells to infiltrate into the tumor microenvironment." (PMID 31832601, 2019). "The overexpression and dysregulation of Hif-1α by genetic alternations or hypoxia have been involved in the biology of cancer, specifically in areas of energy metabolism, angiogenesis and vascularization, tumor invasion and cell survival." (PMID 31791417, 2019). "Thus, HIF1α activation in tumor contributes to Warburg effect, the propensity of tumor cells to utilize glycolysis instead of oxidative respiration even under normoxic conditions." (PMID 30995715, 2019). "Furthermore, both STAT3 and HIF-1α are responsible for the metabolic shift toward aerobic glycolysis, known as Warburg effect, which is typical of highly aggressive tumours." (PMID 31013746, 2019). "Moreover, simultaneous admission of STAT3 and HIF-1α inhibitors significantly increased the anti-tumor activity of cisplatin in TNBC under hypoxic conditions." (PMID 31443516, 2019). "Hence, the HIF-1α/VEGF pathway regulates the deterioration of tumor microenvironments including oxygenation, vessel maturity, blood perfusion, and hypoxia to restrict the efficacy of tumor therapy." (PMID 31695774, 2019). "In an HIF-1α dependent pathway, lactate promotes vascular endothelial growth factor secretion and polarization towards M2 macrophages, which produce Arginase 1, promoting tumor proliferation and growth." (PMID 31468283, 2019). "Our data further emphasized the role of NO which is induced by eATP, which further potentiates glycolytic activity dependent on HIF-1α, and modulation of ATP-NO-HIF-1α axis may confer and contribute to the anti-tumor functions of Th9 cells." (PMID 31164892, 2019). "Given the correlation between NEDD4L and HIF-1α, we hypothesized that they may be jointly involved in tumor development and progression." (PMID 31673244, 2019). "However, our data indicate that the increases in the HIF-1α-positive area can be an indicator of tumor hypoxia and TAITN." (PMID 31336612, 2019). "HIF-1α has been shown to be essential for MDSC function in the tumor environment." (PMID 30804946, 2019).
tumor (continued). "Indeed, the deletion of HIF-1α in TAMs led to reduced tumor progression in the mouse model of breast cancer." (PMID 30708988, 2019). "The median SIRT-3, p-mTOR and nuclear HIF-1α expression levels (percent of immunopositive tumor cells) were 35 (IQR 10–60), 0 (IQR 0–0) and 1 (IQR 0–10) in early-stage patients vs. 60 (IQR 10–90), 0 (IQR 0–0) and 0 (IQR 0–7.5) in advanced-stage patients, respectively." (PMID 30917505, 2019). "CO2 also significantly inhibits tumor growth, tumor new blood vessel formation, and cancer cell invasion by affecting the expression of hypoxia-inducible factor 1-alpha (HIF-1a), vascular endothelial growth factor (VEGF), matrix metalloproteinase-2 (MMP-2), and matrix metalloproteinase-9 (MMP-9)." (PMID 30845750, 2019). "All results indicated that ELTD1 knockdown could inhibit tumor growth and that HIF-1α overexpression could abrogate the ELTD1 knockdown-mediated inhibition of tumor growth." (PMID 31554859, 2019). "Besides, research has revealed that tumor-derived hypoxia inducible factor 1a (HIF-1a) upregulated PD-L1 on MDSCs by binding to a hypoxia-response element (HRE) in the PD-L1 proximal promoter." (PMID 30808413, 2019). "HIF1α-mediated gene regulation is involved in promoting hypoxic suppression of anti-tumor immunity." (PMID 31866995, 2019). "Indeed, glutamine-induced normoxic HIF1α accumulation was significantly reduced in the investigated tumor cells that were treated with acetylsalicylic acid or ibuprofen." (PMID 31554283, 2019). "High levels of R-2-HG also inhibit PHD (prolyl hydroxylases) and the degradation of HIF1-α, favoring tumor formation, growth and survival through the production of vascular endothelial growth factor (VEGF), glucose transporter 1 (GLUT1), phosphoglycerate kinase 1 (PGK1)." (PMID 30708988, 2019). "VEGF is a direct target of HIF-1α and plays an essential role in angiogenesis and tumor metastasis." (PMID 31291975, 2019). "Based on our findings, we suggest that dual HIF-1α/HIF-2α inhibitors are potentially clinically relevant enhancers of tumor radiosensitivity, but that HIF-1α inhibitors alone may increase radiation resistance." (PMID 30642030, 2019). "Increasing evidence is suggesting that HIF-1α could facilitate tumor growth by disrupting metabolic balance, accelerating angiogenesis, increasing cell survival, inhibiting cell apoptosis, as well as increasing drug resistance." (PMID 31022939, 2019). "Combined with our previous study, we could safely draw the conclusion that upregulated SIRT6 in PTC inducing epithelial–mesenchymal transition by positive regulation of HIF-1α, thus promotes tumor progression." (PMID 30675128, 2019). "Taken together, our data suggest that the regulation of TDO2 expression by HIF1α may be involved in modulating anti-tumor immunity in GBM." (PMID 31866995, 2019). "HIF-1α is a key regulator of cellular response to hypoxia and plays an important role in tumor growth by trans-activating various genes that are related to regulation of angiogenesis, energy metabolism, survival, resistance to anti-tumor therapy, and cell survival, apoptosis, and proliferation." (PMID 30678691, 2019). "Furthermore, HIF-1α activates the transcription of many other miRNAs including miR-382, miR-421, miR-191, and miR-687 that promote migration, angiogenesis, metastasis, tumor growth, or drug resistance in cancer." (PMID 31717786, 2019). "By this means, the tumor‐specific production of O2 may reduce hypoxia‐related cytokines (e.g., HIF‐1α) and PD‐L1 to unleash immune‐promoting T cells, which may assist the immunotherapeutic effect of PI3Kγ inhibition in tumor sites." (PMID 31453054, 2019). "In keeping with these results, loss of specific tumor suppressors, such as promyelocytic leukemia protein (PML) or tuberous sclerosis proteins 1 and 2 (TSC1 and TSC2), has been shown to promote HIF-1α expression through suppression of hypoxia-induced inhibition of mTOR." (PMID 31530290, 2019).
tumor (continued). "Collectively, these data suggested that ELTD1 knockdown could inhibit tumor growth and that HIF-1α overexpression could abrogate the effect in vivo." (PMID 31554859, 2019). "From this, we conclude that HIF1a relates more strongly to tumour genetics than to tumour size." (PMID 31323773, 2019). "Similarly, the HIF-1α fluorescence was significantly stronger in the PNP-treated tumours than in those treated with NPs." (PMID 30952842, 2019). "Complementary, SIRT1 may also act as a tumor suppressor by deacetylating HIF-1α lysine 674, blocking p300 recruitment and repressing HIF-1α targets." (PMID 30939818, 2019). "In addition, we have demonstrated that PTBP3 promoted tumor growth and metastasis via enhancing the translation of HIF-1α, as proven by a series of in vitro and in vivo experiments." (PMID 31291975, 2019). "Co-expression of GLUT-1, HK-II, and HIF-1α has been observed in numerous tumor types." (PMID 31105886, 2019). "The normoxic stabilization of HIF1α at the protein level was found in various tumor cell lines after the application of several growth factors (e.g., EGF or insulin) or fetal bovine serum only in the presence of the amino acid glutamine and as a result of glutaminolysis." (PMID 31554283, 2019). "It is tempting to speculate that a secondary effect of pharmacological STAT3 inhibition in cancer therapy may consist in a reduction of IL-15 dependent HIF-1α enrichment in NK cells, which may be expected to improve NK cell anti-tumor activity." (PMID 31681292, 2019). "Further, PIK3CA, MYC, HIF1A and other genes with frequent alterations in primary tumours are known to dysregulate cellular metabolism by increasing the rate of glycolysis while reducing the rate of aerobic respiration; a phenomenon referred to as the Warburg effect." (PMID 31754644, 2019). "HIF1A regulates cellular adaptation to hypoxia and promotes tumor development." (PMID 31744467, 2019). "HIF1α promotes tumor cell proliferation in vivo by promoting ATG5 expression and autophagy levels." (PMID 31700698, 2019). "In addition, previous studies have shown that OSM can promote glycolytic mechanisms in human hepatocyte cell lines in a PDK-1-dependent manner and can induce HIF1α in different cell types to promote tumor progression in cancer cells." (PMID 31555281, 2019). "The quantitative results showed that the hypoxia intensity (pimonidazole and HIF-1α) in PNP-treated tumour sections was two times higher than that in ONP-treated tumour sections, indicating the superior ability of PNPs to create and maintain tumour hypoxia after laser irradiation." (PMID 30952842, 2019). "Studies have demonstrated that activation of PI3K/Akt signaling pathway in tumor cells could induce the expression of HIF-1α protein." (PMID 31531063, 2019). "VEGF expression is modulated by HIF-1α and it is a key pro-angiogenic step for tumor progression." (PMID 31799182, 2019). "Moreover, PTEN/PI3K/AKT regulates the proteasome-dependent stability of HIF-1α under hypoxic conditions and controls tumor-induced angiogenesis and metastasis." (PMID 31036754, 2019). "It was observed that the tumor tissue of saline and soluplus group highly expressed HIF-1α, and r-As4S4 administration mildly down-regulated HIF-1α expression with weak brown color staining in tumor tissue, while much less HIF-1α was detected in the e-As4S4 group." (PMID 31106156, 2019). "In addition to its pivotal role in hypoxia-mediated radioresistance, HIF-1α promotes tumor recurrence after RT by increasing tumor repopulation and protecting tumor blood vascular structure via VEGF production." (PMID 31430901, 2019). "As a key transcriptional regulator, HIF-1α has critical effect on the development and progression of tumor cells by activating the targeting genes, which can regulate several biological processes including cell proliferation, survival, migration, angiogenesis, and glucose metabolism." (PMID 30782196, 2019).
tumor (continued). "Ischemia—as determined by HIF1a expression—is strongly related to tumour genetics in UM." (PMID 31323773, 2019). "HIF1A mediates the hypoxic adaptation of tumor cells and tissues in multiple ways." (PMID 31744467, 2019). "Thus, the hypoxic conditions within the tumor can lead to enhanced stability and activation of HIF-1α." (PMID 30754624, 2019). "Thus, xenograft models have shown that chronic administration of topotecan inhibits HIF-1α expression, angiogenesis and tumor proliferation." (PMID 30708988, 2019). "Next, we explored the activation status of HIF-1α in H1437 IKKαKD cells grown as tumor xenografts in immune-compromised NSG mice or maintained in vitro under hypoxic conditions either as monolayer cells or tumor spheres." (PMID 31792060, 2019). "Therefore, acetylating agents, such as acetylsalicylic acid or ibuprofen, were used to affect the level of HIF1α in different tumor cells." (PMID 31554283, 2019). "Thus, the activation of oncogenes and the inactivation of cancer suppressor genes can increase the expression of HIF-1α and enhance its activity in tumor cells." (PMID 33817155, 2019). "In addition, hypoxia and necrosis were observed in the tumor core, as shown by consistent staining of HIF-1α and compacted nuclei with leakage of cytoplasmic content." (PMID 31117198, 2019). "Although the role of hypoxia and the HIF-1α transcriptional response in promoting tumor progression and metastasis is well established, the direct contribution of the HIF family to the regulation of AA transporters has been less studied, apart from LAT1 and glutamate transporters." (PMID 31152137, 2019). "Thus, suppressing tumour growth by targeting the HIF-1α/VEGF signalling pathway represents a promising strategy for the treatment of HCC." (PMID 31239858, 2019). "Next, we investigated whether laser-stimulated PNPs could be used to maintain tumour hypoxia for longer periods, so we performed pimonidazole and HIF-1α staining at 24 h post irradiation." (PMID 30952842, 2019). "Furthermore, by specifically targeting HIF-1α with small molecule inhibitors, NK cells showed the ability to mediate potent anti-tumor immunity." (PMID 31396523, 2019). "While directly targeting HIF-1α in tumours so far has been unsuccessful, inhibiting the HIF-1α-driven and tumour-secreted Hsp90α may represent an alternative approach." (PMID 31641193, 2019). "We then determined tumor hypoxia by analysis for hypoxia-inducible factor (HIF)-1α." (PMID 31438982, 2019). "The results showed that whether Slug or Ubc9 proteins were co-localized with HIF1α suggesting that Slug SUMOylation may occur in the hypoxic region in tumor." (PMID 30612578, 2019). "At the molecular level, higher levels of HIF-1α were measured in both neurosphere and tumour samples, with the importance of HIF-1α further illustrated through interference experiments, potently suppressing neurosphere formation and stem cell marker expression (CD133, CD15 and NESTIN)." (PMID 31835751, 2019). "Furthermore, the hypoxic environment of tumor tissue stimulates the release of HIF-1α, which upregulates the expression of vascular endothelial growth factor (VEGF) and following angiogenesis for cancer progression." (PMID 31781219, 2019). "Similarly, BAP1-negative tumours (n = 30) had a higher expression of HIF1a (p < 0.001) and a lower expression of VHL (p = 0.003) compared to BAP1-positive tumours (n = 24)." (PMID 31323773, 2019). "HIF-1α staining assay was used to evaluate the tumour hypoxic conditions." (PMID 31671658, 2019). "Moreover, under the hypoxic condition, like those seen in solid tumors, the RON/β-catenin complex binds HIF-1α, which further enhances the tumor growth." (PMID 31085796, 2019). "Hyperthermia increases the activity of NADPH-oxidase in tumor cells, thereby stabilizing HIF-1α." (PMID 31788448, 2019).
tumor (continued). "In the context of cancer, it has been reported that HIF-1α stabilization under hypoxic conditions prevents CD19+ B cells from colonizing the tumor site and is associated with a slower development of the tumor in the early stage of pancreatic cancer development." (PMID 31086070, 2019). "Impairment of nitric oxide (NO) signaling is also associated with MICA/B shedding, and the accumulation of hypoxia-inducible factor-1α (HIF-1α) contributes to the immune escape by increasing ADAM10 expression to decrease surface MIC molecules on the tumor cell." (PMID 31396523, 2019). "Finally, to encompass critical aspects of the interaction between tumor clones and their microenvironment, we simulated responses to hypoxia via the HIF1α pathway and consequent release of signaling molecules such as VEGF." (PMID 31611367, 2019). "Developing anti-tumor drugs targeting HIF-1α/VEGF pathway has become a hot research direction." (PMID 31531063, 2019). "Tumor-derived lactate drives macrophage polarization toward a tumor-promoting phenotype in mice, where HIF-1α-dependent lactate-induced expression of arginase 1 and VEGF might also contribute to immunosuppression and tumor evasion." (PMID 31781212, 2019). "Interestingly, although both series of samples (from tumor core and periphery) displayed a similar protein stabilization of HIF-1α, the activation of transcriptional signatures related to hypoxia or HIF-1α was only observed in core samples." (PMID 31410187, 2019). "HIF-1α has been shown to have a role in UM tumor progression and metastases formation." (PMID 31357444, 2019). "Tumour hypoxia and a subsequent increase in HIF1α expression are consequences of bevacizumab treatment in vivo, which may lead to increased local invasion." (PMID 30850588, 2019). "Deregulated c-myc and HIF-1α cooperate to increase glucose metabolism through the induction of glycolytic enzymes, thus providing adaptive advantages to cancer cells in the hypoxic tumor microenvironment." (PMID 31506466, 2019). "Along similar lines, TAMs exhibit high levels of both HIF-α isoforms in response to hypoxia and, in consonance, myeloid-specific deletion of HIF1α or HIF2α has recently been correlated to reduced tumor growth and better outcome in breast cancer and colon carcinoma, respectively." (PMID 31535086, 2019). "Taken together, our results indicated that HIF1α could promote tumor cell proliferation in vivo by promoting ATG5 expression and autophagy levels." (PMID 31700698, 2019). "Additionally, inhibition of HIF1α through oral administration of BAY 87-2243 also significantly inhibited the tumor growth and metastasis." (PMID 31371307, 2019). "Furthermore, in a hypoxic tumor microenvironment, MDSCs acquire profound immunosuppressive qualities via HIF-1α-stabilization." (PMID 29953680, 2019). "Tumor hypoxia can increase the CSC population through HIF-1α and HIF-2α protein driven responses." (PMID 31382593, 2019). "Moreover, our finding is particularly intriguing in light of the fact that Hif1α also serves a key role in promoting AG in neoplastic tumor cells." (PMID 31609200, 2019). "Tumor perfusion and oxygenation were evaluated using color Doppler ultrasound indices (pulsatility index and resistance index) and the expression of hypoxia inducible factor-1α (HIF-1α)." (PMID 31350968, 2019). "Thus, it has been proposed that, similarly to HIF-1α, NF-κB also plays a pivotal role in reprogramming tumor glycolysis." (PMID 31600993, 2019). "Expression of HIF1a is increased in tumours with monosomy 3 and BAP1 loss, but not with gain of chromosome 8q." (PMID 31323773, 2019). "Proteins differentially secreted by NTMs in response to hypoxia were predicted to be regulated by HIF-1α activation and are known to enhance tumour cell proliferation, invasion, cell movement, angiogenesis, vasculogenesis, and the migration of endothelial cells." (PMID 30813438, 2019). "Hypoxia in tumor cells is also known to activate HIF1α and favor EMT in hypoxic tumor cells." (PMID 31554173, 2019).